IL6 (interleukin 6)
Diseases named in the same sentence as IL6 in open-access papers (continued):
Sharing a sentence is not in itself a finding about the gene and the disease.
breast cancer (continued). "In breast cancer, CK2 enhances IL-6 production to promote tumor progression." (PMID 35832651, 2022). "It is known that non-metastatic breast cancer cells do not express IL-6 and IL-8; our data showed that treatment with IL-1β induced their expressions, through the de-methylation of their promotors." (PMID 36499741, 2022). "Exercise reduces the postoperative levels of IGF-1, IL-6, CRP, IL-10 and TNF-α among patients with breast cancer, which may have a significant impact on inhibiting breast cancer recurrence and improving its prognosis." (PMID 36482346, 2022). "In contrast, our results clearly indicate that IL-6 does not induce VEGF expression in breast cancer." (PMID 34976184, 2022). "The first report on this observation goes up to 1996, when detectable levels of IL6 were found in the conditioned media of ER− but not ER+ human breast cancer cell lines." (PMID 35163731, 2022). "This phenomenon was also evident in breast cancer when breast cancer cells secreted a number of factors, such as transforming growth factor-β1 (TGF-β1), interleukin 1 (IL-1), IL-6 and IL-1114,39–41, all of which suppressed osteoblast differentiation and function." (PMID 35513484, 2022). "Furthermore, a clinical study reported an increase in IL-6, GM-CSF, IFN-γ levels in breast cancer patients undergoing PTX treatment." (PMID 35273508, 2022). "Moreover, our in vivo findings indicated that TAM derived IL-6 induces CSC population and resulting tumor growth in breast cancer." (PMID 35300689, 2022). "Although the molecular mechanism by which GPR81 regulates IL-6 and IL-11 expression remains unclear, it is plausible that lactate controls the production of these cytokines through GPR81 in breast cancer cells." (PMID 35428832, 2022). "Hence, targeting IL-6 or PGE2 reduced DNMT3B induction and enhanced the efficacy of programmed cell death protein 1 (PD-1) immunotherapy in preclinical mouse models of breast cancer metastasis." (PMID 35267528, 2022). "Similarly, high consumption of dietary fibers is inversely related to the circulating inflammatory markers interleukin 6 (IL-6) and tumor necrosis factor α receptor 2 (TNF-α-R2) in postmenopausal women and C-reactive protein (CRP) in breast cancer survivors." (PMID 35160104, 2022). "Thus, our in vivo findings suggest that, TAM derived IL-6 promotes CSC enrichment and tumor growth in breast cancer." (PMID 35300689, 2022). "For this reason, in a female mammary tumor model, we studied whether BPA treatment could affect the intratumoral expression of IL-1β, IL-4, IL-6, IL-10, TNF-α, IFN-γ, and VEGF by confocal microscopy immunofluorescence." (PMID 35269666, 2022). "We conducted two studies to examine differences in post-operative physical and mental functioning, pain, fatigue, and systemic inflammatory markers including interleukin (IL)-6, tumor necrosis factor (TNF)-α, and C-reactive protein (CRP) in women with early-stage breast cancer." (PMID 35941136, 2022). "Therefore, this meta-analysis will focus on the effects of exercise on IL-6, IL-10, IL-1β, CRP, TNF-α, IGF-1 and IGFBP-3 levels in breast cancer patients." (PMID 36482346, 2022). "Regarding this, combination of anti-IL-6 antibody, or multiple pathway inhibitors with trastuzumab maybe novel strategy to reverse drug resistance in HER2+ breast cancer." (PMID 35924148, 2022). "Tang and co-workers demonstrated that HDAC1 can positively regulate the transcription and promoter activities of IL-8, while not IL-6, in breast cancer cells." (PMID 35053925, 2022). "On the other hand, this secretome could be beneficial, as IL-1β was shown to inhibit melanoma growth in vivo, and IL-6, as well as IL-8, could not only induce but also reinforce senescence in the MCF-7 breast cancer cell line." (PMID 35563820, 2022). "Thus, our data indicate that IL-6 alone can enhance breast cancer stemness by regulating CSC phenotype and stem cell specific transcription factors expression in breast cancer." (PMID 35300689, 2022).
breast cancer (continued). "IL6 and COX2 reduced DNMT3b induction and improved response to PD1 therapy in breast carcinoma." (PMID 35226658, 2022). "Our findings suggest there is a robust, IL-6-dependent polarization toward type 3 immunity, which accompanies MDSC expansion in this mammary carcinoma model, and that this altered Th cell landscape should be considered to improve immune and other oncotherapies." (PMID 36142210, 2022). "A large number of studies have shown that IL-6/JAK2/STAT3 signaling pathway is abnormally highly activated in a variety of cancers, such as gastric cancer (GC), breast cancer (BC), liver cancer, colorectal cancer (CRC), colon cancer, ovarian cancer (OC), lung cancer, pancreatic cancer (PC)." (PMID 36591515, 2022). "In inflammatory breast cancer, which is a rare and aggressive type of breast cancer, a number of pathways such as the JAK/STAT, COX2, and IL6 pathways are activated, which have critical biological effects by supporting the escape of cancer cells from detection by the immune cells in the TME." (PMID 34680248, 2021). "Though our models support a role for EphA2‐mediated IL‐6 osteoclast differentiation and osteolysis, we do not yet know if this regulatory pathway also mediates breast cancer cell homing to bone." (PMID 33869989, 2021). "For instance, interleukin-6 (IL6) produced by CAF can enhance the Signal transducer and activator of transcription 3 (STAT3) pathway activation, thus accelerating the proliferation of breast cancer cells." (PMID 33819917, 2021). "The reported upregulation of SHOX2 by STAT3 activation in Helicobacter pylori-infected gastric cancer cells is a cell type-specific effect given that no elevation in SHOX2 was observed in breast cancer cells following IL6-induced STAT3 activation." (PMID 34465361, 2021). "In addition, extracellular ATP promotes the invasion and chemoresistance of breast cancer cells through the sex-determining region Y-box 9 (SOX9) signaling pathway, which interacts with IL-6–Janus kinase 1–STAT3 signaling." (PMID 34638242, 2021). "Activation of βARs in breast cancer cell lines and osteoblasts also induces the production of IL-6, which has the potential to stimulate the βAR-driven pro-angiogenic pathway by promoting the expression of VEGF and the proliferation of breast cancer cells." (PMID 34207620, 2021). "There was higher expression of IL6, MCP1, BCL2, luminal cytokeratins, MUC1, BRCA1, BRCA2, CEA and CA 15-3 in older women with primary breast cancer compared to younger women." (PMID 34165702, 2021). "In basal-like breast cancer (BLBC) cells, IL-6 promotes metastasis by activating DUB3." (PMID 34454495, 2021). "Furthermore, metformin treatment of two primary breast cancer cells MBCDF and MBCD17 downregulated mesenchymal signature genes vimentin and SNAIL and inactivated NFKB and STAT3 signaling pathways in response to IL-6." (PMID 35052372, 2021). "In our study, we confirmed that overexpression of BQ could lead to the activation of IL-6/STAT3 pathway, which conferred resistance to tamoxifen in ER+ breast cancer cells." (PMID 33806019, 2021). "Other cytokines including IL6, IL8, and CXCL1, which similarly drive JAK/STAT, are associated with increased growth and stemness in TNBC but not non-TNBC breast cancer." (PMID 35582030, 2021). "While there are limited or no information on the relationship between TMX treatment and hepatic IL-6 expression, earlier reports have shown that COX-2 may play a vital role as a predictor of adverse effects of TMX in breast cancer patients." (PMID 35049934, 2021). "We assessed the mRNA expression of resistin, tumor necrosis factor-alpha (TNF-α), interleukins 6 and 8 (IL-6, and IL-8), and estrogen receptor alpha (ER-α) in peripheral blood mononuclear cells (PBMCs) of women with and without breast cancer." (PMID 33517609, 2021).
breast cancer (continued). "Interestingly, we also found that NUPR1 depletion in MCF-7TamR cells resulted in decreased pro-migratory cytokine interleukin-6 (IL-6) production, suggesting a role for NUPR1 in the induction of IL-6 expression in Tam resistant breast cancer cells." (PMID 33542201, 2021). "IL-6 is a negative prognostic marker in breast cancer patients mainly due to its role in regulating STAT3 and its downstream targets promoting tumor cell proliferation, survival, and angiogenesis." (PMID 34067421, 2021). "Importantly, IL-6 activates STAT3—as we found in our experiments—giving the IL-6/JAK/STAT3 pathway a key role in tumour progression in a variety of types, including breast cancer." (PMID 34948097, 2021). "TNF-α, IL-6, and IL-8 were significantly reduced after 6 months in the SHD group, but not in the control group, and this indicated that SHD can significantly improve the inflammatory response of patients with breast cancer treated with endocrine therapy." (PMID 34485118, 2021). "CNTD2, NEURL, STAC2, IL6, FREM1, and HOXA4 may be involved in recurrence of LumB-subtype breast cancer." (PMID 33644115, 2021). "In addition, HER2 + breast cancer cells that develop resistance to trastuzumab treatment are enriched with CSCs, exhibit EMT features and express high levels of IL-6." (PMID 34722553, 2021). "Not as expected, there was no obvious change in LINC00467 expression in breast cancer cells with the treatment of IL-6, hypoxia induction or silence of endogenic MYC." (PMID 33996559, 2021). "The IL-6/JAK2/STAT3 pathway has been shown to increase proliferation and migration of ovarian cancer cells, and ovarian cancer patient derived ascites cells, as well as the migration and invasion of breast cancer cells." (PMID 34912237, 2021). "Our results indicated that the mRNA expression of IL-6 significantly increased in PBMCs of breast cancer patients especially in patients without surgery in comparison to those with surgery and healthy controls." (PMID 33517609, 2021). "The observation of not-treated with ME 4T1 breast cancer cells revealed a statistically significant increase in IL-6 mRNA expression after the exposure to heat at 39 °C and 41 °C in comparison to cells cultured at 37 °C (p < 0.05 and p < 0.01, respectively)." (PMID 34201348, 2021). "Our research revealed also that not-treated with ME breast cancer cells display an increased mRNA expression of IL-1β and IL-6 in response to heat at 39 °C alone but not to 41 °C." (PMID 34201348, 2021). "As key inflammatory biomarkers C-reactive protein (CRP) and interleukin-6 (IL6) play an important role in the pathogenesis of non-inflammatory diseases, including specific cancers, such as breast cancer (BC)." (PMID 34572592, 2021). "Other secreted factors are likely to also be involved in supporting metastatic progression, including IL-6 that herein was upregulated in the plasma of tumor-bearing mice and that its tumor expression levels in the METABRIC database predict lower breast cancer patient survival." (PMID 33158447, 2020). "Additionally, we studied 4 more factors that were pointed out by the cytokine array in the current study, but did not pass all our selection criteria, and appeared in the METABRIC breast cancer database: DKK1, IL-6, LIF, and M-CSF." (PMID 33158447, 2020). "Furthermore, adipocyte- or CAA-secreted factors, including leptin, TNF-α, IL-6, IL-1β, IGFBP-2, LCN2, collagen VI, and others, have also been demonstrated to promote breast cancer cell malignant progression, such as EMT, invasion, and metastasis." (PMID 32242230, 2020). "Moreover, IL-6 or leptin can increase procollagen-lysine, 2-oxoglutarate 5-dioxygenase 2 (PLOD2) expression in breast cancer cells through the activation of the JAK/STAT3 and the AKT signalling pathway." (PMID 32033341, 2020).
breast cancer (continued). "The production of inflammatory cytokines such as IL-6, IL-8, and monocyte chemoattractant protein-1 (MCP-1) in both, human hFOB 1.19 and murine M3T3-E1 osteoblasts was increased upon the interaction with metastatic MDA-MB-231 breast cancer cells." (PMID 32092997, 2020). "There might be a reduced inflammatory process via a reduction in TNF-α, IL-6, IL-18, and CRP expression in breast cancer mice that were subjected to moderate intensity exercise." (PMID 32309219, 2020). "Gene expression of MMP1 and MMP11 in PBMC from breast cancer patients (n = 54) and control (n = 28); expression of IL1A, IL6, IL17, IFNβ, and NFĸB in breast cancer cell lines (MCF-7 and MDA-MB-231); and, additionally, IL10 and MMP11 in CAF and NF were analyzed by qRT-PCR before and after co-culture." (PMID 33396463, 2020). "In another study, it was demonstrated that IL-6 upregulates the expression of indoleamine-pyrrole 2,3-dioxygenase (IDO) enzyme via NF-κB activation, thereby enhancing the immunosuppressive function of MDSCs in breast cancer." (PMID 31941522, 2020). "The induction of breast cancer cell lines (MDA-MB-231 and T47D) with the TLR3 ligand induces cellular proliferation through an MyD88-dependent manner via induction of proinflammatory cytokine IL-6 and cyclin D1." (PMID 33072559, 2020). "So, IL-6/JAK/STAT3 signaling is believed as a key signaling pathway for tumor progression, and has been confirmed in many types of solid tumors such as HCC, breast cancer and lung adenocarcinomas." (PMID 33153467, 2020). "MCM and hCM greatly increased the expression of IL-6, IL-1β, IL-1α, TNF-α, IGF-1, and MCP-1 compared with control at the mRNA levels in MCF-7 and MDA-MB-231 cells, while the little effect on the VEGF expression in mCM treated-breast cancer cells." (PMID 32201525, 2020). "Furthermore, the interference of STAT3 (the transfection of si-STAT3) in linc00514-OVE breast cancer cells elevated the mRNA levels of TNF-α, NOS2, and IL-6, and reduced the expression of Arg-1 at both mRNA and protein levels." (PMID 32943090, 2020). "Our results suggest that the PAA-induced ROS deregulated Stat3/IL-6 pathway and PAA may be a potential agent targeting breast cancer and CSCs." (PMID 33202749, 2020). "However, IL1A, IL6, IL10, and NFĸB gene expression in CAF was increased, whereas MMP11 was decreased after co-culture with PBMC from breast cancer patients." (PMID 33396463, 2020). "In this study, we found that Faecalibacterium prausnitzii could inhibit the secretion of IL-6 and the phosphorylation of JAK2/STAT3 in breast cancer cells." (PMID 32272885, 2020). "Deregulated overexpression of IL-6 induces cell proliferation, EMT, stem cell phenotype, angiogenesis, metastasis, cachexia, self-renewal of cancer stem cells, and therapeutic resistance in breast cancer." (PMID 32565805, 2020). "Furthermore, breast cancer cells produce factors such as PTH or PTHrP, IL-1, and IL-6, which stimulate osteoblasts and stromal cells to secrete RANKL." (PMID 32117996, 2020). "Previous studies have illustrated that IL-6 was related to tumorigenesis and EMT of non-small cell lung cancer, distant dissemination of prostate cancer and breast cancer, regeneration and drug resistance of breast cancer stem cells." (PMID 32420905, 2020). "Some other adipocytokines, such as IL-6 and TNF-α released by activated macrophage, results in inflammation, which could be partly responsible for breast cancer development." (PMID 32600328, 2020). "According to previous studies, interleukin-6 (IL-6) can activate JAK2/STAT3 signaling, and repression of the IL-6/JAK2/STAT3 signaling axis has been reported to inhibit the migration, invasion, and tumor formation of breast cancer cells." (PMID 32503225, 2020). "In accordance with our results, researches have demonstrated that CXCR2+ MDSCs were predominately expanded and recruited in breast cancer and could boost EMT of breast cancer cells dependently on IL-6/STAT3 signaling." (PMID 32092078, 2020).
breast cancer (continued). "Indeed, resistin, a main inducer of IL-6, was found to be expressed at greater levels in the TME of AA than of EA patients, specifically in breast cancer cells." (PMID 32714862, 2020). "Quick literature search revealed that PTGS2, EGFR, ABCB1, and IL6 high expression rather than low expression was correlated with breast cancer growth." (PMID 32577155, 2020). "Interleukin 6 (IL-6) may induce EMT and change the phenotype of breast cancer cells towards stemness." (PMID 32456160, 2020). "Moreover, inhibition of autophagy downregulates IL-6 secretion, possibly via the JAK2/STAT3 signaling, in triple-negative autophagy-dependent breast cancer stem cells (BCSCs)." (PMID 32391363, 2020). "Cancer cell-derived IL-6 activates the STAT3 pathway in MDSCs, subsequently upregulating indoleamine 2,3-dioxygenase in co-cultures of human CD33(+) myeloid progenitors with MDA-MB-231 breast cancer cells." (PMID 32726950, 2020). "Breast cancer cell-derived IL-6 promotes IL-6 and IL6Rα expression in MDSCs, and IL-6 trans-signaling in cancer cells activates STAT phosphorylation, thereby promoting breast cancer invasion and metastasis in a mouse model established through a xenograft of human breast cancer cells." (PMID 32726950, 2020). "Meanwhile, the overexpression of linc00514 in breast cancer cells inhibited the THP-1 mRNA levels of TNF-α, NOS2, and IL-6, which are M1 polarization markers of macrophages, while it promoted the expression of Arg-1 at both mRNA and protein levels, which is a M2 polarization marker." (PMID 32943090, 2020). "IL‐6 is another well‐demonstrated inducer of EMT and cancer stem features in breast cancer." (PMID 31860165, 2020). "Moreover, CD200fc, which mimics the effect of CD200, significantly decreased tumor growth and metastasis in a mouse model of breast cancer, increased IFN-γ and decreased IL-6 expression, and time-dependently altered IL-10 and IL-17 levels." (PMID 32635224, 2020). "Additionally, tumor growth is promoted by IL-6 via the IL-6/JAK2/STAT3 pathway in kidney, lung and breast cancer, and angiogenesis in prostate cancer patients was found to be associated with TGFβ." (PMID 31988649, 2020). "The incubation with Faecalibacterium prausnitzii supernatant could inhibit the secretion of IL-6 and the phosphorylation of JAK2/STAT3 in breast cancer cell line MCF-7." (PMID 32272885, 2020). "Therefore, we aimed to investigate the effects of exercise on inflammatory cytokines interleukin (IL)-6, IL-18, tumor necrosis factor-α (TNF-α), and C-reactive protein (CRP) in a breast cancer mouse model." (PMID 32309219, 2020). "Moreover, serum IL6, IL8, and TNFα are related to an advanced stage and metastatic status of breast cancers, whereas IL6 and IL8 are most favorable for prognosis." (PMID 31398937, 2019). "Co-culture of macrophages with breast cancer cells induces sustained release of TNF-α and IL-6 from both cell types, resulting in activation of NF-κB, STAT3, and ERK-1 and hyperphosphorylation of ERα (rendering it constitutively active) in the breast cancer cells." (PMID 30736340, 2019). "Knowing that inflammation plays a major role in breast cancer pathogenesis, we sought to elucidate whether OSM and IL-1β work together to promote IL-6 secretion in breast cancer." (PMID 31007849, 2019). "This study proposed the upregulation of PIM1 by IL-6 contributed to breast cancer cell aggressiveness and targeting PIM1 or c-myc could be novel approaches for breast cancer treatment." (PMID 30989585, 2019). "High levels of CRP and cytokines (mainly IL6, IL1ß, and sTNF-RII) have been also reported in others studies among breast cancer survivors with cognitive impairment that suggested a dysregulation of the immune system as a possible mechanism of onset of cognitive decline." (PMID 31795208, 2019). "In this study, we found that STAT3 could also mediate IL-6-induced MMP2 and MMP9 expression and breast cancer cell migration." (PMID 31409371, 2019).